RN7SL51P (RNA, 7SL, cytoplasmic 51, pseudogene)
Gene: Miscellaneous RNA gene on chromosome 2 (62,262,387 to 62,262,671, reverse strand). Ensembl gene ENSG00000239958.
Homologues: Orthologues: chimpanzee Metazoa_SRP (98% identical), macaque Metazoa_SRP (94% identical), dog Metazoa_SRP (73% identical). Paralogues in human: RN7SL1 (78% identical), RN7SL2 (78% identical), RN7SL122P (77% identical), RN7SL3 (77% identical), RN7SL218P (76% identical), RN7SL441P (76% identical), RN7SL7P (76% identical), RN7SL126P (76% identical), RN7SL321P (76% identical), RN7SL448P (76% identical), RN7SL516P (75% identical), RN7SL566P (75% identical), and 703 more.